GLI2 (GLI family zinc finger 2)
Diseases named in the same sentence as GLI2 in open-access papers (continued):
Sharing a sentence is not in itself a finding about the gene and the disease.
leukemia (12 papers, 2014 to 2025). A malignant (clonal) hematologic disorder, involving hematopoietic stem cells and characterized by the presence of primitive or atypical myeloid or lymphoid cells in the bone marrow and the blood. "Of the genes more highly expressed in female FLT3‐ITD‐positive AML, the hedgehog signalling mediator GLI2 has been associated with FLT3‐ITD‐mutated leukaemia, while HOXB‐AS3 is reportedly upregulated in NPM1‐mutated AML, and has been implied to contribute in regulation of AML cell‐cycle progression." (PMID 34101344, 2021). "The treatment reduced the burden of GLI2-expressing leukaemia stem cells, their dormancy (enhancing cycling), and sensitised the cells to tyrosine kinase inhibition." (PMID 38612718, 2024). "Our work addresses the role of smoothened (SMO) activation of its downstream hedgehog pathway transcriptional activator, GLI2, in human myeloid leukemia progression, leukemia stem cell self-renewal and dormancy." (PMID 25889765, 2015). "Hh receptor molecules are lost in several leukemia cell lines, including KG-1 cells; however, the transcription factor Gli2 is expressed." (PMID 25009639, 2014). "In these systems, LSC burden decreased commensurate with GLI2 and cell cycle regulatory gene repression and while GLI2 overexpression enhances dormant human leukemia stem cell generation, selective inhibition of SMO abrogates it and sensitizes them to tyrosine kinase inhibitors." (PMID 25889765, 2015). "Studies have shown that glasdegib abrogates leukemia-initiation potential and leukemia stem cell dormancy in chronic myeloid leukemia (CML) and acute myeloid leukemia (AML) cells, most likely due to downstream GLI2 inhibition." (PMID 26891329, 2016). "The present study revealed that TGF-β, alone or combined with TNF-α, was able to decrease the expression level of Gli2 in the KG-1 cell line, thus suggesting that TGF-β may be one of the signaling molecules that plays a key role in the regulation of the Gli2 gene in leukemia cell lines." (PMID 25009639, 2014).
ovarian carcinoma (12 papers, 2014 to 2026). A malignant neoplasm originating from the surface ovarian epithelium. "Zinc finger protein GLI2 functions as a dynamic oncogene in ovarian cancer cells, causing cellular differentiation and proliferation, and as a moderator in the Hedgehog signalling pathway." (PMID 37845675, 2023). "Among them, GLI2 has been shown to be upregulated in benign tumors and ovarian cancer tissues, and it regulates surviving isoform expression in ovarian cancer." (PMID 40565540, 2025). "High expression and cellular trafficking of GLI2 lead to the overactivation of Hedgehog (HH)-targeted genes, thereby accelerating the progression of malignant tumors, especially in the context of ovarian cancer." (PMID 37845675, 2023). "For the remaining genes, GLI2 increases abnormally in benign tumors and ovarian cancer tissues, and regulates the survivin isoform expression in ovarian cancer." (PMID 33244318, 2020). "The effect of bortezomib on hedgehog transcriptional activity (as determined by PTCH1, GLI1, GLI2 gene expression) in SKOV3TRip2 cells led us to evaluate this compound in other ovarian cancer cell lines." (PMID 25216523, 2014). "We analyzed the mRNA expression profiles of HH-related genes—SHH, HHAT, PTCH1, GLI1, GLI2, GLI3, and SUFU—in two ovarian cancer cell lines." (PMID 40565349, 2025). "Immunohistochemistry analysis demonstrated abnormally increased Gli2 and MMP-7 expression levels in benign tumors and ovarian cancer tissues." (PMID 41465326, 2025). "To assess their potential prognostic value, we analyzed the correlation between the expression levels of the following eight components of the Hedgehog signaling pathway on the progression-free (PFS) and overall survival (OS) in ovarian cancer: SHH, GLI1, GLI2, GLI3, PTCH1, PTCH2, HHAT, and SUFU." (PMID 40565349, 2025). "In our study, GLI2 as a downstream target of the Hippo signalling pathway was highly expressed due to the negative regulation by MIR502, resulting in an acceleration of the pathological process of ovarian cancer." (PMID 32660514, 2020).
Culler-Jones syndrome (11 papers, 2018 to 2025). "Mutations in GLI2 have been implicated in both Culler-Jones syndrome (CJS) and holoprosencephaly type 9 (HPE9)." (PMID 41488893, 2025). "In conclusion, this case reports a previously unrecognized truncating GLI2 mutation in a neonate who presented with hallmark features of Culler-Jones syndrome." (PMID 41488893, 2025). "Here, we identify and functionally validate a novel truncating variant in the activation domain of GLI2 linked to a Culler-Jones syndrome phenotype characterized by hypopituitarism, polydactyly and facial dysmorphism in an Italian family." (PMID 30629636, 2019). "The clinical spectrum of mutations in GLI2 may vary from asymptomatic individuals to polydactyly, functional and structural abnormality in the pituitary gland, facial dysmorphism, Culler-Jones syndrome, HPE-like syndrome, and frank HPE." (PMID 31782289, 2020). "Pathogenic variants in these genes cause Huntington's disease (HTT), some cardiomyopathies and muscular dystrophies (TTN), Culler-Jones syndrome, and Holoprosencephaly 9 (GLI2)." (PMID 36651276, 2023). "Defects in the GLI2 gene can cause autosomal dominant holoprosencephaly (OMIM 610829) and Culler-Jones syndrome (OMIM 615849)." (PMID 36360323, 2022). "Clinical manifestations associated with GLI2 mutations range widely, from individuals with no apparent abnormalities to those presenting with polydactyly, craniofacial dysmorphisms, pituitary defects, Culler-Jones syndrome, and holoprosencephaly type 9 (HPE9; OMIM: 610829)." (PMID 41488893, 2025).
lung carcinoma (11 papers, 2012 to 2025). "Our findings that lncRNA MIR31HG stimulates GLI2 by WDR5/MLL3/P300-mediated active chromatin landscape highlight lncRNA MIR31HG as a potential target for clinical lung cancer clinic treatment." (PMID 37950038, 2024). "Spheroid culture and quantification also indicated increased growth of lung cancer stem cells upon GLI2 transfection and shRNA targeting GLI2 retarded spheroid formation of lung cancer cells." (PMID 37950038, 2024). "Our mechanistic investigation revealed that MIR31HG promoted cancer stem cell-related malignant properties of lung cancer cells via H3 histone modification of GLI2 transcriptional activity and its downstream stemness-related molecules." (PMID 37950038, 2024). "Drug sensitivity assay showed that GLI2 overexpression significantly (p < 0.01) enhanced drug resistance of lung cancer cells against targeted EGFR inhibitors and conventional chemotherapy drugs." (PMID 37950038, 2024). "Here, we aimed to investigate how MIR31HG influenced lung cancer stem cell-mediated drug resistance, cellular invasion, and stemness features by epigenetically modulating GLI2 expression using mechanistic and functional analyses." (PMID 37950038, 2024). "To provide a biological meaning of the GLI1 and GLI2 genes in lung cancer, we used the Xena browser analysis for comparison of normal and tumor GLI gene transcripts." (PMID 32033067, 2020). "Together our study suggests that the FGFR1/GLI2 axis promotes the lung cancer stem cell-like phenotype." (PMID 26936993, 2016). "We further assessed the effect of genetic inhibition of GLI2 on the stem-like phenotype of lung cancer cells." (PMID 26936993, 2016). "Although ED-1 cells arose from transgenic lung cancers that activated the HH pathway, these cells had relatively low basal Gli1 and Gli2 mRNA levels and low basal Gli1-reporter activity." (PMID 22923130, 2012). "To determine whether MIR31HG functions through GLI2, we first investigated the function of GLI2 regarding lung cancer stemness-related cellular proliferative advantage and drug resistance." (PMID 37950038, 2024). "Knockdown of GLI2 counteracted MIR31HG-induced cell proliferation, metastasis, and cancer stem cell-mediated multidrug resistance of lung cancer cells." (PMID 37950038, 2024). "In the present study, we showed that GLI2 can be epigenetically upregulated at the transcriptional level by MIR31HG, exerting lung cancer cell stemness-related multidrug resistance, and cellular invasion." (PMID 37950038, 2024). "In lung cancer, GLI Family Zinc Finger 2 (GLI2) acts as the downstream gene of FGF19/FGFR4, and GLI2 can directly transcriptionally upregulate FGF19 expression, forming the FGF19-GLI2-FGF19 feedback loop to promote metastasis." (PMID 36923538, 2023). "Together, these results showed that GLI2 was involved in FGFR1-dependent Hedgehog signaling pathway, which was critical for maintaining the stem-like phenotype of FGFR1 -amplified lung cancer cells." (PMID 26936993, 2016). "Herein for the first time we demonstrated that FGFR1 promoted stem cell-like phenotype in lung cancer cells harboring FGFR1 amplification, especially in LSCC, partly through stimulating the expression and activity of GLI2." (PMID 26936993, 2016).
cervical carcinoma (10 papers, 2015 to 2025). A carcinoma arising from either the exocervical squamous epithelium or the endocervical glandular epithelium. "Knocking down GLI2 in cervical cancer cells can cause suppressed cell growth and migration." (PMID 38924029, 2024). "Phosphorylation of JNK and promotion of ERS occur due to the up-regulation of GLI2 expression following the knockdown of YTHDF2 in cervical cancer cells." (PMID 38776708, 2024). "Hh signaling is involved in the development of cervical cancer; the expression of all signaling molecules of this pathway (Shh, PTCH, Smo, Gli-1, Gli-2, and Gli-3) is increased in cervical carcinoma and is very rarely found in normal cervical epithelium." (PMID 39274874, 2024). "The protein level of GLI2 was examined by introducing SP600125 into cervical cancer cells in which YTHDF2 was knocked down." (PMID 38776708, 2024). "The same thing was observed in cervical cancer, that overexpression of GLI2 increased proliferation." (PMID 32660514, 2020). "Taking together, both GLI1 and GLI2 significantly inducedSOX18 promoter activity in all three cervical carcinoma cell lines, with the strongest effect observed in HeLa cells." (PMID 26588701, 2015). "It has been reported that GLI2 ablation inhibits xenograft growth of cervical cancer cells in vivo." (PMID 35382824, 2022). "Finally, we demonstrated that inhibition of SOX18 function, using dominant-negative approach, inhibits to some extent GLI1/GLI2-mediated migration of cervical carcinoma cells in vitro." (PMID 26588701, 2015). "JNK inhibitors were applied to cervical cancer cells transiently expressing GLI2, and it was found that ERS occurs due to phosphorylation of JNK after the up-regulation of GLI2 expression." (PMID 38776708, 2024). "Semi-quantitative analysis of GLI1, GLI2 and GLI3 in cervical cancer cells demonstrated elevated levels of GLI1 transcripts particularly in HPV16-positive SiHa cells." (PMID 27678330, 2016).
hypopituitarism (10 papers, 2019 to 2025). A condition of diminution or cessation of secretion of one or more hormones from the anterior pituitary gland. "This case expands the phenotypic spectrum of GLI2‐related disorders and reinforces that non‐truncating GLI2 variants are often associated with isolated hypopituitarism and subtle craniofacial or neurodevelopmental features." (PMID 40908550, 2025). "A novel de novo GLI2 variant (p.Arg499Leu) was identified in a child with hypopituitarism and subtle craniofacial and neurodevelopmental features, broadening the clinical spectrum of GLI2‐related disorders and supporting genotype–phenotype correlations." (PMID 40908550, 2025). "Culler–Jones syndrome (CJS) is an autosomal dominant disorder characterized by hypopituitarism, postaxial polydactyly, and craniofacial anomalies, associated with pathogenic GLI2 variants." (PMID 40908550, 2025). "According to existing literature, GLI2 mutations commonly result in hypoglycemia, hypopituitarism, and abnormalities in neurological development." (PMID 41488893, 2025). "This case expands the phenotypic and mutational spectrum of GLI2‐related disorders and highlights the diagnostic value of exome sequencing in children with unexplained hypopituitarism and syndromic short stature." (PMID 40908550, 2025). "The presence of polydactyly in a patient with hypopituitarism or in family members should therefore prompt consideration of a GLI2 mutation." (PMID 41488893, 2025). "Another challenge of molecular diagnosis in hypopituitarism is the presence of variants with incomplete penetrance, as reported in two families with GLI2 variants in this study." (PMID 39156017, 2024). "Disease‐causing variants in GLI2 have been associated with a spectrum of phenotypes, ranging from isolated pituitary hormone deficiencies to classic HPE and CJS, which is characterized by the triad of postaxial polydactyly, hypopituitarism, and craniofacial anomalies." (PMID 40908550, 2025). "Serial endocrine follow‐up is planned to monitor for the potential emergence of additional pituitary hormone deficiencies, as GLI2‐related hypopituitarism may evolve over time." (PMID 40908550, 2025). "Previous studies indicated that GLI2 is related to the morphogenesis of hair follicles and the proliferation and apoptosis of dermal papilla cells and suggested that GLI2 mutations may lead to congenital hypopituitarism." (PMID 39794979, 2024). "In certain GLI2 variants, IGHD (13%), hypopituitarism with unspecified hormone deficiencies (6%), and HH (2%) have also been associated." (PMID 34948037, 2021). "Hitherto, the GLI2 gene was not linked to nIHH but was evidenced to impact pituitary function in hypopituitarism." (PMID 39010903, 2024). "HESX1, GLI2, and SOX3 mutations have been linked to hypopituitarism, and mutations in SOX2, LHX3, LHX4, and PROP1 may cause gonadotropin deficiency." (PMID 34948037, 2021). "In conclusion, extra-pituitary findings may provide clues for the diagnosis of particular gene mutations including GLI2, HESX1, LHX4, SOX3, and OTX2 which are involved in the development and differentiation of the pituitary gland resulting in a variety of pituitary hormone deficiencies." (PMID 31782289, 2020).
liver fibrosis (10 papers, 2012 to 2025). "Gli2 was upregulated in CCl4-induced liver fibrosis and its conditional deletion in HSCs ameliorated CCl4-induced liver fibrosis and HSC activation." (PMID 40260391, 2025). "In particular, the Smo–Gli2 axis, an activator of Hh signaling, is crucial in orchestrating liver fibrosis." (PMID 37371128, 2023). "Follow-up immunofluorescence results of mIBECs and histological analysis of livers of BA mice also demonstrated increased fibrosis markers in mIBECs and more pronounced liver fibrosis in BA mice after overexpression of GLI2." (PMID 35692978, 2022). "Consistently, immunofluorescence staining revealed that injection of Ad-miR-223 reduced GLI2 expression in HSCs in CCl4-induced liver fibrosis." (PMID 33867837, 2021). "Administration of miR-223 inhibited liver fibrosis by inhibiting the transcriptional coactivator with PDZ-binding motif (TAZ)-Indian hedgehog (IHH)-GLI Family Zinc Finger 2 (GLI2) pathway via the crosstalk between hepatocytes and HSCs." (PMID 33867837, 2021). "The SHH signaling is suggested to be mediated through its immediate target GLI2 in hepatic fibrosis since GLI1 expression was found rather sparse in HSCs." (PMID 24312641, 2013). "In the same context, the current results reveal the correlation between the hepatic fibrosis prompted by DEN and the marked stimulation of Hh signaling, as clarified by the amplified gene expressions of Ptch1 as well as Gli1 and Gli2." (PMID 36811777, 2023). "In contrast, when GLI2 was silenced with lentivirus, the EMT-related factors and liver fibrosis markers in mIBECs changed in the opposite trend to those after overexpression, and the degree of liver fibrosis was partially reversed in BA mice." (PMID 35692978, 2022). "As the data obtained from the in vitro experiments indicated that TB4, acting via SMO and GLI2, was critical to the fate of HSCs, we examined the in vivo effect of TB4 on hepatic fibrosis in mice overexpressing the Tb4 gene (Tb4-Tg)." (PMID 28630423, 2017). "In conclusion, the present study demonstrated that TB4 enhanced the activation of SMO-GLI2 by regulating the expression of ILK and pGSK3b, as well as interacting with SMO and GLI2, thereby promoting HSC activation and liver fibrosis." (PMID 28630423, 2017). "Then, GLI1/GLI2 was silenced and overexpressed in mouse intrahepatic bile duct epithelial cells (mIBECs) and BA animals to investigate changes in the mRNA and protein expression of EMT key factors and liver fibrosis indicators." (PMID 35692978, 2022). "After silencing and overexpression of GLI1/GLI2, immunofluorescence was used to detect the expression of cytokeratin-19 (CK19) and α-smooth muscle actin (α-SMA) in mIBECs, and hematoxylin and eosin (HE) staining and Masson staining were used to observe the degree of liver fibrosis in the BA animals." (PMID 35692978, 2022).
lung fibrosis (10 papers, 2013 to 2025). "CircRNA‐662 and 949 can function as miR‐29b sponges to regulate STAT3 and Gli2, which are the main regulatory factors of lung fibrosis." (PMID 31448882, 2019). "In our research, we found that Gli1 was increased much more significantly than the expression of Gli2 in the development of pulmonary fibrosis." (PMID 29844390, 2018). "The GLI-2/3 inhibitor that is GANT61 decreases lung fibrosis." (PMID 35681469, 2022). "Recent studies have shown that GLI-1 and GLI-2 play a major role in pulmonary fibrosis." (PMID 27486656, 2016). "Moreover, a study involving the use of a mouse model reported that treatment with GLI-1 siRNA and GLI-2 siRNA markedly inhibited the progression and severity of interstitial pulmonary fibrosis." (PMID 27486656, 2016). "Moreover, GLI-1 is observed in fibroblast, epithelial cells, and inflammatory cells (cytoplasmic and nuclear localization), whereas GLI-2 is detected in alveolar epithelial cells, primarily in a nuclear distribution, where the whole data indicate the activation of Shh signaling during lung fibrosis." (PMID 35681469, 2022). "Therefore, GLI-1 and GLI-2 play a critical role in interstitial pulmonary fibrosis." (PMID 27486656, 2016). "Lung tissues from patients with idiopathic pulmonary fibrosis have increased expression of GLI1 and GLI2 when compared to normal lung tissues." (PMID 35008794, 2021). "For instance, TGF-ß, a growth factor that plays a critical role in lung fibrosis and in cancer development, interacts with Hh pathway downstream of SMO, increasing the expression of Gli2 in mice and in cancer cells." (PMID 23667589, 2013). "Signal transducer and activator of transcription 3 (STAT-3) and zinc finger protein (Gli-2) are pro-fibrotic molecules which are involved in pulmonary fibrosis, and it was found that circRNA-662 and circRNA-949 have sponge like activity against miR-29b which interacts with STAT-3 and Gli-2." (PMID 38321530, 2024). "In contrast, it was recently demonstrated that mice deficient in Gli1 were not protected from lung fibrosis suggesting either Gli2 or non-canonical hedgehog signaling may be regulating pathological effects in lung fibrosis." (PMID 32218238, 2020).